TIMP1 (TIMP metallopeptidase inhibitor 1)
Diseases named in the same sentence as TIMP1 in open-access papers (continued):
Sharing a sentence is not in itself a finding about the gene and the disease.
breast carcinoma (continued). "TIMP1 could be a promising target for preventing metastasis; TIMP1 that was incorporated into extracellular vesicles was found to promote metastasis of colorectal cancer to the liver, and TIMP1 gene expression was strongly associated with breast cancer metastasis to lymph nodes." (PMID 36768435, 2023). "We verified one of these interactors, CD74, as a TIMP‐1 cell surface binding protein in breast cancer cells." (PMID 37081824, 2023). "We show here that CD74 is involved in the internalization of TIMP‐1 by breast cancer cells and that TIMP‐1‐mediated activation of Akt signaling is dependent on CD74." (PMID 37081824, 2023). "miR-107 was shown to negatively regulate NEAT1 expression and regulate breast cancer progression through affecting the tumor development-associated genes, including TIMP-1, PDGF-A, SERPINB2, cyclin D1, CDK4, and CPA1A in breast cancer cells." (PMID 37310654, 2023). "CD74 is thought to promote breast cancer metastasis, so we decided to focus our attention on its putative interaction with TIMP‐1 in breast cancer cells." (PMID 37081824, 2023). "Briefly, we have identified multiple TIMP‐1 interactors and verified that CD74 is a novel TIMP‐1 cell surface binding protein in breast cancer cells." (PMID 37081824, 2023). "We found that our 3D tumor model involving the co‐culturing of hASCs and breast cancer cells showed increased ECM protein deposition on the surface due to TIMP‐1 overexpression, thereby inhibiting ECM degradation." (PMID 35600659, 2022). "A large number of research studies suggested that TIMP1 is often highly expressed in several types of human cancer cells, containing prostate cancer, lung cancer, melanoma, breast cancer, and glioblastoma." (PMID 35685428, 2022). "In monolayer culture, stromal cells showed a higher TIMP‐1 protein expression than breast cancer cells." (PMID 35600659, 2022). "More recently, TIMP-1 levels were described as prognostic factors of shorter PFS in patients with a metastatic HER2 + breast cancer treated with lapatinib or trastuzumab." (PMID 35818030, 2022). "When hASCs were co‐cultured with breast cancer cells, TIMP‐1 protein expression was increased by approximately 1.25 times compared to that when the two cells were cultured separately." (PMID 35600659, 2022). "The upregulation of TIMP1 was relative to poor prognosis of multiple cancers including colon cancer, breast cancer, gastric cancer, melanoma, papillary thyroid carcinoma, renal cell carcinoma, and so on." (PMID 35281807, 2022). "In breast cancer, TIMP-1 expression in primary tumor tissues is an independent poor prognostic factor." (PMID 36741729, 2022). "Immunohistochemistry identified a concordance between high TIMP1 levels and a high rate of distant metastasis in breast cancer and TIMP1, in serum of ovarian cancer patients with preoperative, is also associated with more aggressive tumor behavior." (PMID 36158681, 2022). "In turn, STAT3 increases TIMP-1 secretion by breast cancer cells, leading to a TIMP-1/CD63/integrin β1/STAT3 positive feedback loop, which can be further fueled by IL-6." (PMID 36291767, 2022). "HAS2 promotes the invasion of breast cancer cells by decreasing tissue metalloproteinase inhibitor 1 (TIMP-1)." (PMID 36613567, 2022). "On the other hand, TIMP‐1, which is mainly expressed in breast cancer, was highly upregulated in hASC‐co‐cultured spheroids at both the RNA and protein levels compared to the other models." (PMID 35600659, 2022). "In a 2008 study conducted on 60 breast cancer patients, high serum levels of both MMP-9 and TIMP-1 were also associated with lower progression-free and OS rates." (PMID 35818030, 2022). "For example, high serum levels of TIMP1 are promising indicators of poor overall survival of breast cancer patients, whereas high serum levels of MMP-9 have been demonstrated to strongly predict response to treatment and metastasis." (PMID 35818030, 2022).
breast carcinoma (continued). "The purpose of this study was to elucidate the role of CAF-secreted TIMP-1 for the effects of CAFs on breast cancer cell behavior." (PMID 36291767, 2022). "Here, we present data showing that CAF-derived TIMP-1 activates STAT3 in breast cancer cells in cooperation with CD63 and integrin β1." (PMID 36291767, 2022). "The effect of co‐culturing with stromal and breast cancer cells on TIMP‐1 expression was also investigated." (PMID 35600659, 2022). "Many investigations have shown that among various isoforms of TIMPs, the expression of TIMP‐1 correlates with the progression and severity of several types of cancers, including colon cancer, lung carcinoma, gastric cancer, melanoma, and breast cancer." (PMID 35600659, 2022). "CAF-derived TIMP-1 was involved in the migration and growth of breast cancer cells though TIMP-1/CD63/ITGB1/STAT3 feedback loop." (PMID 36741729, 2022). "Authors have identified the novel mechanism of the neutrophil-mediated induction of EMT in breast cancer cells by regulating TIMP-1." (PMID 36091114, 2022). "For BCSC-immune cell cross-talk, LGALS1-PTPRC, NECTIN2-CD96, and NECTIN2/4-TIGIT are found to hamper immunity against breast cancer; by expressing TIMP-1, BCSC promotes epithelial-mesenchymal transition (EMT) by interacting with CD63 in epithelial cells." (PMID 34611125, 2021). "Our results show that TIMP1 promotes the occurrence and development of GC, which is consistent with previous reports about TIMP1 as an oncogene in other cancers, including breast cancer, colon cancer, glioblastoma, and non-small cell lung cancer." (PMID 34775375, 2021). "HAS2 increases breast cancer cell invasion through inhibiting tissue metalloproteinase inhibitor 1 (TIMP-1)." (PMID 33892667, 2021). "Specifically, the TIMP1 can degrade cyclinB1 and activate the NF-κB signaling pathway to protect breast cancer cells against chemotherapy-induced cell death." (PMID 34848810, 2021). "Other alterations in MMP-9 and TIMP-1 levels have been observed in subjects with breast cancer compared to controls." (PMID 32392801, 2020). "By analyzing the publicly available scRNA‐seq data of human primary breast cancer, we confirmed that TIMP1 expression in CAFs with high CD63 expression was significantly higher than in CAFs with low CD63 expression." (PMID 33173749, 2020). "TIMP1 has been demonstrated to be involved in the progression of tumors involving lung adenocarcinoma, glioma, prostate cancer, breast cancer, colorectal cancer and a number of other cancers." (PMID 32420905, 2020). "According to a previous study, TIMP-1 levels are upregulated in non-small cell lung cancer and advanced breast carcinoma." (PMID 31998645, 2019). "Some studies have showed a relationship between higher TIMP-1 levels and a worse prognosis in patients with breast cancer." (PMID 31514476, 2019). "As a result, TIMP-1 was proposed as a potential marker for prediction of response to chemotherapy in breast cancer." (PMID 30583560, 2018). "A previous study revealed that knockdown of TIMP-1 suppressed cell proliferation and cancer development by the inhibition of NF-κB signaling in breast cancer." (PMID 30486830, 2018). "The results reported in the available literature regarding TIMP-1 correspond to the results of the current study and to our previous publications regarding breast cancer." (PMID 28662671, 2017). "In epithelial breast cancer cells, TIMP1 induced TWIST1 expression, leading to E-cadherin downregulation and epithelial mesenchymal transition in a CD63-dependent manner." (PMID 28430130, 2017). "Overexpression of TIMP-1 is associated with VEGF expression and promoting neovascularization in breast carcinoma rats." (PMID 29234409, 2017). "On the contrary, genes such as PDGF-A, SERPINB2, TIMP1, which have been associated to poor prognosis, invasion and metastases, were down-regulated in CPT1A silenced breast cancer cells." (PMID 26799588, 2016).
breast carcinoma (continued). "The results showed that the percentages of CC, CT, and TT of TIMP-1 rs4898 were differentially distributed at 28.5%, 33.1% and 38.4% in the breast cancer patient group and 34.5%, 41.0% and 24.5% in the control group, respectively (P for trend = 7.99*10-13)." (PMID 26872812, 2016). "For example, in MDA-435 breast cancer cells, TIMP-1 was reported to promote cell growth by inhibiting MMPs." (PMID 27130446, 2016). "Numerous studies have demonstrated that TIMP-1 levels are elevated in several types of human cancer, including breast cancer." (PMID 27130446, 2016). "When TIMP-1 plasma levels were measured in breast cancer patients a plasma median level of 81.5 ng/ml (range 41.9–174.9 ng/ml) was found." (PMID 27619981, 2016). "The expression level of TIMP-1 in breast cancer tissues was analyzed using the ONCOMINE microarray database." (PMID 27130446, 2016). "To determine if DNA methylation is associated with the transcriptional silencing of TIMP-1 in different subtypes of breast cancer, we analyzed the promoter sequence of TIMP-1." (PMID 27130446, 2016). "The overall survival of patients with distinct molecular subtypes of breast cancer stratified by TIMP-1 expression levels was evaluated using Kaplan–Meier analysis." (PMID 27130446, 2016). "TIMP-1 is a well-documented antiapoptotic marker as well as a prognostic marker in many cancers particularly breast cancer." (PMID 26366732, 2015). "Assessment of TIMP-1 status was performed retrospectively on primary tumor whole-tissue sections by immunohistochemistry and tumor samples were considered positive if epithelial breast cancer cells were stained by the anti-TIMP-1 monoclonal antibody VT7." (PMID 24884504, 2014). "Among these, MMP-1, 2, 9, 11, TIMP-1, 2 levels have been largely investigated in breast carcinoma tissues." (PMID 25510449, 2014). "The purpose of the present study was to evaluate TIMP-1 immunoreactivity as a prognostic and predictive marker in advanced breast cancer patients receiving docetaxel (D) or gemcitabine plus docetaxel (GD)." (PMID 24884504, 2014). "Taken together, these findings, along with the results obtained in the present study, make a ‘broader’ predictive role of TIMP-1 in the treatment of breast cancer likely." (PMID 24884504, 2014). "TIMP-1 was shown to have cell growth promoting properties in a variety of cancer cell lines including breast carcinoma cells and leukemic cell lines." (PMID 24457057, 2014). "In particular, shed SDC-1 expression is reported to regulate the expression of TIMP metallopeptidase inhibitor 1 (TIMP-1), urokinase plasminogen activator receptor (uPAR), and E-cadherin in breast cancer cells coordinating their invasiveness." (PMID 24551591, 2014). "In summary, this retrospective analysis applied to a prospective clinical trial demonstrated that TIMP-1 status appears to contain an independent prognostic value regarding overall survival in patients with advanced breast cancer receiving chemotherapy." (PMID 24884504, 2014). "TIMP-1 was reported to have prognostic and predictive value in breast cancer, and serum TIMP-1 was a predictor of survival outcomes in colorectal cancer." (PMID 24015777, 2013). "In conclusion, this validation study of TIMP-1 breast cancer cell immunoreactivity as a predictive biomarker for adjuvant anthracycline benefit did not support the use of this marker to select patients for anthracycline treatment." (PMID 23570501, 2013). "The overall intra-variation was 2.5% (range: 0.8-6.8% (median: 1.9%)) (N = 16) for the MMP-9:TIMP-1 measurements in breast cancer plasma, while the inter-variation between plates was 19.9% (range: 11.3-29.2% (median: 19.6%)) (N = 16)." (PMID 24330623, 2013). "UEA fucosylation pattern of TIMP-1 were also analyzed in six different cancers (breast cancer, colon cancer, hepatocellular carcinoma, ovarian cancer, lung cancer, and prostate cancer)." (PMID 24015777, 2013).
breast carcinoma (continued). "We screened plasma from 465 patients with primary breast cancer for prognostic value of the MMP-9:TIMP-1 complex." (PMID 24330623, 2013). "It has been shown that total TIMP-1 levels in plasma and tissue extracts from breast cancer patients are only weakly correlated, and the current findings suggest that the same holds true for TIMP-1 complexes." (PMID 24330623, 2013). "The precision and performance of the MMP-9:TIMP-1 proximity assay was investigated by analysing four breast cancer plasma samples for their levels of MMP-9:TIMP-1 complex and the GFP spike-in." (PMID 24330623, 2013). "Breast cancer cells overexpressing TIMP-1, a well-known inhibitor of matrix metalloproteinase, exhibit a reduced sensitivity to the chemotherapeutic drugs paclitaxel and epirubicin through the activation of transcription factor NF-κB." (PMID 23671674, 2013). "The breast cancer patients were dichotomized into high and low TIMP-1 groups based on a median value of 270 ng/mL." (PMID 22339939, 2012). "Gene expression profiling has identified TIMP-1 within a basal marker subcluster (mesenchymal subcluster) in breast cancer cell lines including MDA-MB-231 cells." (PMID 22957045, 2012). "In summary, this work identifies a novel combination of molecular targets involved in NOS2/TIMP-1/Akt pro-survival signaling, which influence breast cancer outcome within a specific tumor subpopulation." (PMID 22957045, 2012). "A high serum TIMP-1 was significantly associated with HER2 ECD positivity and a poorer DFS among Taiwanese primary breast cancer patients with HER2 overexpression." (PMID 22339939, 2012). "In conclusion, several publications demonstrated a biologic role for TIMP-1 in breast cancer whereas information on CAIX is limited." (PMID 21745383, 2011). "In contrast to breast cancer where up to 75% of the tumours appear to be TIMP-1 positive we only scored 12.3% of the cells as TIMP-1 positive." (PMID 20459644, 2010). "Apart from differences in the assessment of TIMP-1 immunoreactivity this dissimilarity can also be explained by a genuine difference between breast cancer and ovarian cancer." (PMID 20459644, 2010). "Recently, we reported the clinical value of this technology to evaluate the expression of MMP-1, -2, -7, -9, -11, -13 and –14, and TIMP-1, -2 and 3, in breast cancer." (PMID 17848954, 2007). "RZG has been shown for instance to reduce the expression/activity of MMPs in a PPARγ-independent manner in adrenal and pancreatic tumour cells and to increase the expression of TIMP-1 in breast cancer cells." (PMID 16969347, 2006). "A study examining the effect of MCF-7 cells on human dermal fibroblasts found a similar observation, in that the breast cancer cells augmented the production of proMMP-1, -2, and -3 as well as TIMP-1 by fibroblast cells." (PMID 16168111, 2005). "The relationship between expression of MMP-13 and TIMP-1 and the mode of tumor invasion [MI] was evaluated immunohistochemically, using breast carcinoma tissue as a positive control." (PMID 15291964, 2004). "TIMP1 has also been linked to paclitaxel resistance, where higher TIMP1 levels in tumor tissues were associated with poor response to paclitaxel-based therapy in breast cancer, though this has not been observed in other cancers." (PMID 40427104, 2025). "In contrast to these studies, another study suggested that low TIMP1 expression levels may serve as an independent prognostic and predictive biomarker for breast cancer." (PMID 40565366, 2025). "Additionally, the enzyme's influence extends to interactions between membrane CD74 and TIMP‐1 in breast cancer, promoting internalization and Akt signalling activation." (PMID 39074261, 2024). "Breast cancer is a highly heterogeneous disease and our data cannot unequivocally tell us whether the TIMP‐1/CD74 interaction is of pathophysiological relevance regarding tumor progression or response to treatment." (PMID 37081824, 2023).
breast carcinoma (continued). "Additionally, TIMP-1 was found to predict the therapeutic response to several therapeutic modalities such as endocrine therapy in breast cancer and anthracycline-containing chemotherapy in pancreatic ductal carcinoma." (PMID 36551979, 2022). "High levels of blood MMP-9 and TIMP-1 indicate worse prognoses in lung cancer and breast cancer." (PMID 35629249, 2022). "In reference to MMP-9 and TIMP-1, a significant correlation has been previously reported between serum expression and breast disease severity score, suggesting the potential application of its measurement in monitoring breast cancer progression." (PMID 35222743, 2022). "Data from the spheroids with TIMP‐1‐silenced hASC and breast cancer cells indicated that TIMP‐1 might play a key role in the regulation of ECM protein expression." (PMID 35600659, 2022). "Similar TIMP-1 mediated phenomena have been observed in pancreatic and breast cancer." (PMID 35200382, 2022). "Despite its diverse roles in breast cancer, it remains unclear whether TIMP‐1‐dependent ECM regulation affects the penetration or movement of drugs in cancer tissues." (PMID 35600659, 2022). "To investigate the factors that affect the increased expression of TIMP‐1 in the hASC co‐culture model, we analyzed the TIMP‐1 expression in stromal cells under various conditions, including culturing as a monolayer, 3D spheroid culture, and co‐culturing with breast cancer cells." (PMID 35600659, 2022). "Moreover, studies have demonstrated that breast cancer patients with high levels of serum TIMP-1 have a significantly shorter survival." (PMID 36741729, 2022). "In Roquin2-overexpressing MDA-MB-468 and MCF7 cells, we found that proangiogenic factors mRNA, including PDGFC, ENG, EDN1, and VEGFB, were downregulated in two breast cancer cells, while the mRNA expression of antiangiogenic genes, including TIMP1/3, SERPINF1, and ANGPTL4 were upregulated." (PMID 34345214, 2021). "Additionally, we identified a significant association of genes involved in treatment response in breast cancer with genes producing splicing-derived neoepitopes (ERBB2, ESR1, TIMP1, ABCC3) or potentially depleted self-epitopes (AKT1, CCNE1, RET, TFF3)." (PMID 34529669, 2021). "TIMP-1 is one of the tissue inhibitors of matrix metalloproteinases (MMP), the expression of which was previously linked with worse prognoses in melanoma, multiple myeloma, and breast cancer." (PMID 34204115, 2021). "Furthermore, secreted TIMP-1-EGFP hybrid protein was shown to translocate into the nucleus of a human breast cancer cell line MCF-7." (PMID 34270579, 2021). "In addition, a positive feedback loop is achieved by TANs facilitating EMT in breast cancer through TIMP-1 secretion, while CD90+ breast cancer cells that undergo EMT in turn reinforce TAN infiltration through cell-cell interactions." (PMID 34202411, 2021). "A comprehensive literature search showed that TIMP-1 expression in breast cancer, GC and CRC was strongly upregulated compared to that in other cancers, which indicated that TIMP-1 might play a more important role in gastrointestinal cancer." (PMID 33628641, 2021). "Overall, the molecular characterization of CTCs from advanced TNBC patients identifies highly specific biomarkers with potential applicability as noninvasive prognostic markers and reinforced the value of TIMP1 and AR as potential therapeutic targets to tackle the most aggressive breast cancer." (PMID 32012729, 2020). "TIMP-1 was described for its inhibitory activity on metalloproteinase, but there have been conflicting reports on its anti-apoptotic activity and its role in stimulating cell proliferation in breast cancer." (PMID 33042020, 2020). "These dysregulations were associated with lymph node metastases and lower overall survival rates, suggesting that the levels of MMP-9 and TIMP-1 could be further evaluated to predict prognosis and progression of breast cancer." (PMID 32392801, 2020).